PRKG1 (protein kinase cGMP-dependent 1)
Diseases named in the same sentence as PRKG1 in open-access papers (continued):
Sharing a sentence is not in itself a finding about the gene and the disease.
glioma (3 papers, 2016 to 2023). A benign or malignant brain and spinal cord tumor that arises from glial cells (astrocytes, oligodendrocytes, ependymal cells). "PRKG1 is differentially overexpressed in the sphere phenotype in four human glioma stem cell lines, i.e., HF2303, MGG8, IN859 and IN2045." (PMID 27564115, 2016). "This combined network linked both PRKG1 and CFTR to genes already known to be of importance in glioma biology such as PDGFRA, met, and TGFβ2, amongst others." (PMID 27564115, 2016). "Thus, PRKG1 represents a novel therapeutic target to inhibit growth of glioma stem cells." (PMID 27564115, 2016). "And AKT and PRKG1 were also kinases of HSPB1, which indicated that ipatasertib could be an indirect inhibitor of HSPB1 to enhance glioma ferroptosis." (PMID 37158834, 2023).
metabolic syndrome (3 papers, 2019 to 2023). A cluster of metabolic risk factors for CARDIOVASCULAR DISEASES and TYPE 2 DIABETES MELLITUS. "PRKG1 is involved in the gap junction pathway and is related to metabolic syndromes." (PMID 33407101, 2021). "Seven genes (WDR27, GNAS, DOK7, EDN3, MCF2L, PRKG1, and CMYA5) were selected based on genomic location and relevance to metabolic syndrome." (PMID 31170227, 2019). "We investigated the correlation of DNA methylation with expression of seven genes (WDR27, GNAS, DOK7, EDN3, CMYA5, PRKG1, and MCF2L) selected on the basis of their known functions in metabolic syndrome, and their locations in functional genomic regions." (PMID 31170227, 2019).
anemia (2 papers, 2021 to 2025). A reduction in the number of red blood cells, the amount of hemoglobin, and/or the volume of packed red blood cells. "In Prkg1-deficient mice, anemia and splenomegaly were reported, and with the progression of the anemia, a progression of the splenomegaly was found." (PMID 34064290, 2021). "Our findings are in accordance with the findings in global Prkg1-KO mice, which developed an iron deficiency caused by anemia as a follow of the gastrointestinal bleedings, which why we assume (chronic) blood loss as the direct cause of the iron deficiency in global Irag1-deficient mice." (PMID 34064290, 2021). "In the first description of splenomegaly and anemia in global Prkg1-KO mice, a reduced life span of erythrocytes was mentioned and justified with the expression of the PKGI in erythrocytes." (PMID 34064290, 2021). "Treatment with PPI normalized the blood parameters so that global Prkg1 mice show no iron deficiency anemia and splenomegaly." (PMID 34064290, 2021). "The comparison between the blood parameters of IRAG1-KO mice and global Prkg1-KO mice shows that IRAG1-KO mice suffer from a milder form of anemia." (PMID 34064290, 2021). "In this context, it is important to mention that mice with a selective mutation in the N-terminal protein interaction domain of PKGIα (LZM mice) do not develop anemia and have no reduced life span, contrary to global Prkg1-KO mice." (PMID 34064290, 2021).
aortic aneurysm (2 papers, 2018 to 2025). A ruptured aneurysm located in the wall of the proximal portion of the descending aorta proceeding from the arch of the aorta. "As GUCY1A3 and PRKG1 have already been clearly linked to MMS with esophageal achalasia and inherited aortic aneurysm respectively, the role of NO pathway in moyamoya pathogenesis warrants further investigation." (PMID 30001348, 2018).
Hearing impairment (2 papers, 2017 to 2020). A decreased magnitude of the sensory perception of sound. "However, PDE5 inhibitor (vardenafil) has also been demonstrated to protect against noise induced hearing loss (NIHL) through activation of protective cGMP-dependent protein kinase type I (Prkg1) signaling in mouse and rat models." (PMID 29163231, 2017).
Marfan syndrome (2 papers, 2021 to 2023). A disorder of the connective tissue. "Moreover, the inhibition of overexpressed PRKG1 could limit vascular sclerosis to reverse aortopathy in Marfan syndrome mice, suggesting that PRKG1 might be important in blood vessel activity." (PMID 38097986, 2023). "Heritable thoracic aortic disease affecting the elastin–contractile unit, including PRKG1 mutations, may have extra-aortic features, such as hypermobility or cutis laxa, Marfan syndrome-like or Ehlers–Danlos-like features, without fulfilling the diagnostic criteria for these syndromes." (PMID 33807627, 2021).
acute GVHD (1 paper, 2021). "PRKG1 protein is expressed in the skin, stomach and colon, tissues that are targets of acute GVHD." (PMID 34868058, 2021).
aneurysm (1 paper, 2021). Bulging or ballooning in an area of an artery secondary to arterial wall weakening. "The therapy of PRKG1-associated TAA is surgical, according to the guidelines and further monitoring for other aortic dilatations and aneurysms, including of the descending thoracic and abdominal aorta." (PMID 33807627, 2021).
asthma (1 paper, 2025). "In humans, PRKG1 has functions in bronchodilation and asthma." (PMID 40822650, 2025).
attention deficit-hyperactivity disorder (1 paper, 2012). A disorder characterized by a marked pattern of inattention and/or hyperactivity-impulsivity that is inconsistent with developmental level and clearly interferes with functioning in at least two settings (e.g. at home and at school). "Interestingly, the mammalian PKG with highest homology to for, PRKG1, has been associated with Attention Deficit/Hyperactivity Disorder, a condition characterized by a persistent lack of attention possibly due to a failure to habituate to large amounts of information received from the environment." (PMID 23284741, 2012).
bladder cancer (1 paper, 2024). "The results showed that the expression of both MEK1/2 and p-MEK1/2 did not change significantly, indicating a different mechanism of PRKG1 in bladder cancer development." (PMID 39139561, 2024). "The results showed expression of PRKG1 was lower in bladder cancer, compared with normal tissues both at protein and transcript levels." (PMID 39139561, 2024). "cGMP-dependent protein kinase 1 (PRKG1) has shown to be associated with some tumorigenesis, while the role of PRKG1 in bladder cancer is unclear." (PMID 39139561, 2024). "To investigate the biological and clinical significance of PRKG1 in bladder cancer, we detected the expression of PRKG1 and explored the function of PRKG1 in bladder cancer cells." (PMID 39139561, 2024). "In the present study, we detected the expression of PRKG1 in bladder cancer tissues and explored the role of PRKG1 in bladder cancer progression and therapy resistance." (PMID 39139561, 2024). "The relationship between PRKG1 and clinicopathologic characteristics in patients with bladder cancer from FFPE cohort." (PMID 39139561, 2024). "Generally, a lower expression of PRKG1 could be observed in bladder cancer tissues compared with normal tissues, which is also related to higher tumor grade and muscle invasion." (PMID 39139561, 2024). "Thus, activation or over-expression of PRKG1 might play an anti-tumor role in bladder cancer." (PMID 39139561, 2024).
idiopathic scoliosis (1 paper, 2021). A scoliosis with no known cause. "Of interest, PRKG1 is a novel negative regulator of osteoblast differentiation in human skeletal stem cells, and PRKG1 was found to have increased expression in idiopathic scoliosis, where it may become a therapeutic target." (PMID 33807627, 2021).
keratoconus (1 paper, 2021). A degenerative, structural disorder of the eye, characterized by a cone-shaped protrusion of the cornea. "The PRKG1 pathogenic variants described to date are c.530>A (pArg177Gln), and c.1108G>A (p.Gly370Ser)—the latter are associated with abdominal aneurysm, arterial tortuosity and keratoconus." (PMID 33807627, 2021).
Leukoencephalopathy (1 paper, 2025). This term describes abnormality of the white matter of the cerebrum resulting from damage to the myelin sheaths of nerve cells. "Several genome-wide association studies (GWAS) have identified single-nucleotide polymorphisms (SNPs) in the following genes: TRIO, PRKG1, ANK1, COL4A2, NTN1, and ASTN2 that were associated with increased risk of MTX-induced neurotoxicity and leukoencephalopathy on imaging in patients with ALL." (PMID 41029358, 2025).
Patent ductus arteriosus (1 paper, 2024). In utero, the ductus arteriosus (DA) serves to divert ventricular output away from the lungs and toward the placenta by connecting the main pulmonary artery to the descending aorta. "Various genes, including ACTA2, MYH11, MYLK, and PRKG1, have been identified to be responsible for hereditary non-syndromic TAAD, which is typically accompanied by patent ductus arteriosus (TAAD/PDA)." (PMID 38773466, 2024).
psychosomatic disorders (1 paper, 2025). "This review first outlines how epigenetic dysregulation contributes to psychosomatic disorders through altered expression of genes such as GRM2, TRPA1, SLC6A4, NR3C1, leptin, BDNF, NAT15, HDAC4, PRKCA, RTN1, PRKG1, and HDAC7." (PMID 41439979, 2025).
retinitis pigmentosa (1 paper, 2020). Retinitis pigmentosa (RP) is an inherited retinal dystrophy leading to progressive loss of the photoreceptors and retinal pigment epithelium and resulting in blindness usually after several decades. "Based on this, inhibition of Prkg1 is currently explored as a neuroprotective treatment to delay degeneration of photoreceptors in retinitis pigmentosa." (PMID 33374621, 2020).
serous ovarian cancer (1 paper, 2021). "The expression profiles of SDF2L1, PPP1R12A, and PRKG1 were associated with the clinical outcomes of high-grade serous ovarian cancer." (PMID 34745201, 2021).
trachoma (1 paper, 2018). "NPSR1 interacts with phospholipase C and like both PRKG1 and PREX2 (the best candidate associated gene from the trachoma GWAS) is part of the G protein-mediated cascade of intracellular signalling that centres around the PI3K/Akt pathway of cell cycle regulation." (PMID 29967566, 2018).
urothelial bladder cancer (1 paper, 2024). "However, the expression panels of PRKG1 in urothelial bladder cancer remain unclear." (PMID 39139561, 2024).
cancer (39 papers, 2010 to 2025). A tumor composed of atypical neoplastic, often pleomorphic cells that invade other tissues. "A previous study has revealed that PRKG1 is downregulated in tumors from liver, pancreas, lung, and colon and can regulate cancer cellular function." (PMID 39139561, 2024). "Some researchers focused on the role of PKG in some cancers, but only a few studies detected the clinical significance of PRKG1." (PMID 39139561, 2024). "PRKG1 improves the activity and invasion of cancer cells, and it is also indicated that PRKG1 plays a role as an intermediary in the epidermal growth factor receptor (EGFR)-mediated cell death, likely via apoptotic pathway." (PMID 29301256, 2018). "(b) The crucial role of dysregulated signalling pathways in cancer development, and the frequent therapeutic targeting of kinases, makes association with the cyclic GMP-dependent protein kinase PRKG1 a plausible finding." (PMID 21827660, 2011). "We found that five genes were related to cancer, including BNIPL, ERBB3 and PRKG1, which were also been detected by degree or eigenvector measures." (PMID 29301256, 2018). "Furthermore, the expression of top 5 genes (DCHS1, PRKG1, TGFBR2, TNS1, and TTC28) in the majority of detailed cancer types was shown in the form of heatmap." (PMID 36051999, 2022).
tumor (33 papers, 2012 to 2026). "The lower expression of PRKG1 is associated with a higher tumor grade and muscle invasion." (PMID 39139561, 2024). "The present study firstly identified the anti-tumor role and tumor immune regulatory role of PRKG1, also found loss of PRKG1 could be used as a prognosis factor." (PMID 39139561, 2024). "A lower expression of PRKG1 was associated with higher tumor grade, T stage, and muscle invasion." (PMID 39139561, 2024). "Lower PRKG1 expression was related to higher tumor grade, T stage, and muscle invasion, also predicted worse overall survival and recurrence free survival in patients treated with Bacillus Calmette–Guerin (BCG) intravesical immunotherapy." (PMID 39139561, 2024). "The results indicate the regulatory role of PRKG1 in BCa immunotherapy and its potential to be used as a biomarker for tumor immunotherapy." (PMID 39139561, 2024). "The results showed that PRKG1 expression was negatively correlated with DNAss, which indicated lower PRKG1 corresponded to stronger tumor cell stemness." (PMID 39139561, 2024). "Cox regression analysis revealed that muscle invasion and lower PRKG1 were indicators of tumor recurrence." (PMID 39139561, 2024). "Analysis of tumor immune cells infiltration showed lower PRKG1 was associated with non-inflamed tumor microenvironment." (PMID 39139561, 2024). "In addition, the relation between PRKG1 expression and the infiltration level of tumor immune cells in tumor microenvironment were analyzed." (PMID 39139561, 2024). "It warrants future in vivo testing to determine whether activation of PRKG1 reduce tumor burden and extends survival either alone or in combination with standard therapy." (PMID 27564115, 2016). "Meanwhile, tumor suppressors, including KLF12, PRKG1, TRPS1, NOTCH1, RORA, were downregulated in the HSPA8high group." (PMID 33926391, 2021). "We also observed that tumor suppressors, including KLF12, PRKG1, TRPS1, NOTCH1, and RORA, were downregulated in the HSPA8high group." (PMID 33926391, 2021). "In our study, 10q11.23 (PRKG1), 10q22.1 (CSTF2T), 10p12.33 (MRC1), and 10p12.1 (STAM) occurred in 37.5% of ChRCC and not in RO, indicating the potential of the two cytobands in differentiating the two tumours." (PMID 39684226, 2024).
infection (16 papers, 2013 to 2025). The state of being infected such as from the introduction of a foreign agent such as serum, vaccine, antigenic substance or organism. "In addition, the PI3K-Akt signaling pathway-related genes were expressed at lower levels in SFTSV infection 24 and 48 h, for example, GP1BA, PIK3CA, PIK3CB, AKT3, PRKG1, and PRKG2." (PMID 37211158, 2023).
heart disease (7 papers, 2017 to 2025). "Another motif, ELDKY, is shared in multiple human proteins, such as PRKG1 involved in platelet activation and calcium regulation, and tropomyosin, which is linked to cardiac disease." (PMID 35891400, 2022).
vasculopathies (1 paper, 2018). "MRVI1 is a functional partner of other genes (ITPR1, PRKG1 and GUCY1A3), differently related to MMS and other vasculopathies, but together involved in response to NO." (PMID 30001348, 2018).
PRKG1 also shares sentences with these, for which no sentence is quoted: cardiac hypertrophy (22 papers); ischemia (10); endothelial dysfunction (8); melanoma (7); cardiovascular diseases (6); colorectal cancer (6); atherosclerosis (5); Hyperglycemia (5); Myocardial fibrosis (5); neuroblastoma (5); Stroke (5); memory impairment (4); multiple sclerosis (4); myocardial ischemia (4); neurodegenerative disease (4); renal fibrosis (4); breast tumor (3); Coma (3); coronary artery disease (3); depression (3); diabetic nephropathy (3); dilated cardiomyopathy (3); erectile dysfunction (3); hypertrophic cardiomyopathy (3); Insulin resistance (3); liver fibrosis (3); osteoporosis (3); ovarian cancer (3); Parkinson disease (3); cardiomyopathy (2).
A further 94 diseases each share a sentence with PRKG1 in 2 papers or fewer.